TNF (tumor necrosis factor)
Diseases named in the same sentence as TNF in open-access papers (continued):
Sharing a sentence is not in itself a finding about the gene and the disease.
sarcoidosis (continued). "Early experience with TNF antagonists in sarcoidosis has been primarily based on the use of infliximab for cutaneous and extracutaneous sarcoidosis." (PMID 19830230, 2009). "There is evidence that TNF is involved in the pathogenesis of sarcoidosis, and there have been numerous reports of the successful treatment of sarcoidosis with TNF antagonists." (PMID 19830230, 2009). "ILD due to sarcoidosis was characterized by increased cytokine levels of TNF-α compared with healthy donors (1.2 versus 0 pg/ml)." (PMID 19615053, 2009). "Because of extensive spleen involvement and his history of diabetes, and because therapy with TNF antagonists has been shown to be efficacious in the treatment of sarcoidosis, treatment with adalimumab 40 mg every other week was prescribed." (PMID 19830230, 2009). "Thalidomide, an immunomodulatory agent has the ability to inhibit all of the inflammatory mediators specific to sarcoidosis, and, particularly, has very potent activity against TNF-α." (PMID 18226232, 2008). "Novel treatment strategies for sarcoidosis have been developed including the use of TNF-alpha inhibitors, such as infliximab." (PMID 18811966, 2008). "Recent advances on the knowledge of sarcoidosis pathogeny suggest that the overproduction of tumor necrosis factor α (TNF-α) at the sites of disease plays a pivotal role." (PMID 18021432, 2007). "It is intriguing to note that there is a positive correlation between S100A8/A9 expression and TNF-α release in alveolar macrophages from patients with active sarcoidosis." (PMID 16613612, 2006). "Our aim was to study the role of tumour necrosis factor α (TNF-α) and interleukin-1 (IL-1) in the suppressive activity of alveolar macrophages on autologous lung fibroblasts proliferation in sarcoidosis." (PMID 18475478, 1992). "TNF, an inducer of EMT, is abundantly expressed by monocytes from both sarcoidosis and TU patients, which might help explain the therapeutic efficacy of TNF inhibition in these disorders." (PMID 40469525, 2025). "The genotyping of the TNF-α G-308A polymorphism may serve as a possible indicator for predicting the therapeutic efficacy of TNF-α treatment in sarcoidosis." (PMID 39904950, 2025). "Elevated levels of IL-2, TNF-α, and other pro-inflammatory molecules are frequently observed in sarcoidosis and may serve as indicators of disease activity or progression." (PMID 40078389, 2025). "It is hypothesized that anti-TNF-α-induced sarcoidosis may result from imbalances involving TNF receptor 2 (TNFR2) and T-regulatory cells." (PMID 40647656, 2025). "TNF-α, a potent proinflammatory cytokine produced primarily by alveolar macrophages, plays a critical role in regulating and perpetuating granuloma formation in sarcoidosis." (PMID 39061958, 2024). "However, TNF-α inhibitors can sometimes even induce a paradoxical reaction with the development of a sarcoidosis-like reaction." (PMID 38654341, 2024). "TNF-α induces the accumulation and differentiation of macrophages into epithelioid cells and multinucleated giant cells, promoting the formation of granulomas that are characteristic of sarcoidosis and sarcoidosis-like reactions." (PMID 39590170, 2024). "Moreover, in relation to other anti-TNF-α agents such as infliximab, etanercept and adalimumab, sarcoidosis after certolizumab seems to be less-commonly reported." (PMID 39180528, 2024). "In sarcoidosis, TNF-α produced by macrophages is thought to be involved in granuloma formation." (PMID 39478628, 2024). "This case serves as a reminder to consider sarcoidosis in the differential diagnosis of patients presenting with respiratory symptoms or radiographic findings suggestive of granulomatous disease undergoing TNF-α antagonist therapy." (PMID 39180528, 2024). "Sarcoidosis blood ILC1s induced genes involved in TNF signaling and the JAK/STAT pathway." (PMID 39225100, 2024).
sarcoidosis (continued). "Cytokines integral to these reactions, like IL-6 and TNF-α, typically rise in chronic inflammatory diseases such as sarcoidosis, stimulating muscle protein degradation, retarding protein synthesis, and consequently invoking catabolic processes in muscle tissue." (PMID 39395132, 2024). "However, the use of TNF-α inhibitors in the treatment of sarcoidosis is challenging due to potential side effects and the significant costs associated with treatment." (PMID 39061958, 2024). "Further potential hypotheses on the pathogenesis of anti-TNF-mediated sarcoidosis have been proposed." (PMID 37175894, 2023). "Therefore, we have identified a set of immunological parameters including Treg suppressive function, TNFα, TNFR I and II, sCD25 and Ki-67+ that are associated with clinical features in sarcoidosis." (PMID 38173720, 2023). "Higher serum TNF expression was previously reported in SFN due to sarcoidosis compared to controls." (PMID 36604634, 2023). "PTHrP immunoreactivity and/or mRNA in the cytoplasm of sarcoid macrophages and multinucleated giant cells were observed in more than half of lymph node biopsies in patients with sarcoidosis TNF-α and IL-6, may stimulate PTHrP production in sarcoid macrophages." (PMID 37358786, 2023). "Indeed, this is quite in keeping with that anti TNF-α therapy in patients with sarcoidosis led to increased PB lymphocyte counts." (PMID 37161980, 2023). "In addition to symptomatic treatment with steroids, treatment with TNF-α–neutralizing antibodies and Janus kinase inhibitors has been considered for sarcoidosis." (PMID 38038136, 2023). "TNF-α G-308A polymorphism has been shown to influence clinical outcomes in sarcoidosis patients treated with infliximab and adalimumab.In this review, we reported six studies on the anti-TNF-α intervention that resulted in partial to complete resolution of CS lesions after several months." (PMID 37818515, 2023). "In sarcoidosis, the number of macrophages is generally increased in the lung with high production of several mediators, such as TNF-a and are considered to be central in sarcoidosis pathogenesis as they activate T-cells, produce pro-inflammatory cytokines that drive inflammation." (PMID 37445947, 2023). "Lack of TNFSFR1B expression of Treg may lead to non-functional Treg which suggests a functional influence on the effect of anti-TNF therapy of sarcoidosis." (PMID 37621457, 2023). "The reason TNFα may be inferior to IL-1β at reflecting granuloma formation is unclear, but TNFα levels in sarcoidosis tissues are known to vary greatly based, in part, on disease activity." (PMID 37021060, 2023). "In this case, Propionibacterium acnes was detected in the granulomas, suggesting that P. acnes infection may show aberrant responses to drugs such as TNF-α inhibitors and immune checkpoint inhibitors, consequently leading to drug-induced sarcoidosis." (PMID 37175894, 2023). "The immune response in the pathogenesis of sarcoidosis is characterized by a bias toward the Th1 response, with the release of cytokines and chemokines associated with this type of immune response (e.g., IFN-γ, TNF-a, and often IL-2)." (PMID 37761266, 2023). "Since IFN-γ and TNF-α production by CD4+ T cells is hardly inhibited by Tregs in active sarcoidosis patients, we considered infliximab treatment as a chance for reducing inflammation, counteracting changes of immune cell frequencies and thereby ameliorating PML." (PMID 34993476, 2022). "Furthermore, SAA has the potential to stimulate production of TNF, IL-10 and IL-18 in lung cells from patients with sarcoidosis." (PMID 36543347, 2022). "This suggests that FCGR1A could serve as therapeutic target to mitigate TNF mediated immune dysregulation in sarcoidosis." (PMID 36311769, 2022).
sarcoidosis (continued). "More recent data from Jenyet al. suggest that macrophages differentiated from monocytes isolated from patients with active sarcoidosis (n=26) were more sensitive to hypoxic challenge in vitro than those isolated from patients with inactive sarcoidosis, producing more TNF-α, IL-1β and TGF-β1." (PMID 36543347, 2022). "Tumour necrosis factor-alpha (TNF-α) plays an essential role in the pathophysiology of sarcoidosis." (PMID 35264154, 2022). "The direct link was proven by the disappearance of the sarcoidosis picture when the anti-TNF treatment stopped, which could in fact be a rebound to the immunosuppression-induced inflammatory disease with pulmonary expression." (PMID 36421591, 2022). "Along with extensive IFN-γ production in the lungs of sarcoidosis patients, the expression of cytokines, including pro-inflammatory cytokines, such as TNF, IL-12, IL-18, and IL-6, and regulatory cytokines, such as TGF-β and IL-10, has been reported to be upregulated in affected tissues." (PMID 35615369, 2022). "The pathogenetic pathway of sarcoidosis is still poorly defined, but a Th1-like cytokine pattern characterized by increased levels of TNF-α, IFN-γ, and T-cell responses may play an important role." (PMID 34802085, 2022). "Targeted TNF therapy was the first biological therapy used in patients with sarcoidosis." (PMID 36148463, 2022). "Interestingly, some reports describe the paradoxical development of sarcoidosis in patients using TNF-α inhibitors." (PMID 37205958, 2021). "TNF-α inhibitors are used as a third-line treatment option for sarcoidosis." (PMID 34233893, 2021). "Clinicians should be aware of the possibility of sarcoidosis in patients under anti-TNF therapy." (PMID 34641810, 2021). "Upon stimulation with PMA and ionomycin in vitro, there is an increase of IFN-γ and TNF-α producing CD56bright NK cells in BALF from sarcoidosis patients, which may imply involvement of NK cells in granuloma formation." (PMID 34868074, 2021). "Insight into how TNF-α inhibitors influence these cells may provide more information on inflammatory mechanisms in sarcoidosis and improve understanding of such treatment." (PMID 34233893, 2021). "Finally, the inflammatory phenotype of MD-macrophages in pulmonary sarcoidosis and their propensity to produce TNFα has been recently highlighted, supporting the role of these cells in sarcoidosis pathogenesis." (PMID 34456926, 2021). "TNF-α is a proinflammatory cytokine that has been extensively targeted clinically with blocking antibodies for rheumatoid arthritis, inflammatory bowel disease, and sarcoidosis." (PMID 32582173, 2020). "However, treatment options in patients with multidrug-refractory sarcoidosis failing initial anti-TNF therapy is a challenging issue in clinical practice." (PMID 33330556, 2020). "IL1-β, TNF and IL-6 are all fundamentally associated with sarcoidosis, and CCL2 is a potent chemotactic agent for monocytes and T cells, and is strongly increased in BAL fluid of sarcoidosis patients." (PMID 32948789, 2020). "Moreover, usage of TNF inhibitor (infliximab or adalimumab) was more frequent in BD (48.9%) than in sarcoidosis (10.5%), VKH (29.4%), and SSc (0%)." (PMID 31513650, 2019). "The median TNF-α concentration was also significantly higher in sarcoidosis PBMCs (2375 pg/mL, IQR 691–6578) compared to healthy volunteer PBMCs stimulated with sKv (42.82 pg/mL, IQR 12.8–107.7, p = 0.0003) or sarcoidosis PBMCs stimulated with cKv (10.25 pg/mL, IQR 2.05–19.56, p = 0.0001)." (PMID 28114394, 2017). "Since this monocyte subset has been shown to express the highest levels of the TNF receptor TNFR131, monocytes in sarcoidosis may be more responsive to TNF." (PMID 27929051, 2016).
sarcoidosis (continued). "Patients with sarcoidosis had a significantly higher secretion of inflammatory cytokines tumour necrosis factor-alpha (TNF-α), interleukin-6 (IL-6), IL-10 and IL-12 (1.7-fold, 2.0-fold, 2.2-fold, and 2.8-fold, respectively; all p < 0.05) after in vitro co-stimulation of PBMCs with FCWAs and LPS." (PMID 27688795, 2016). "Low monocyte CD200R expression was associated with heightened TNF and IL-6 production in response to PHA stimulation, and blockade of CD200R or CD200L in healthy controls led to increased TNF and IL-6 secretion by monocytes, recapitulating the hyper-activated monocyte state seen in sarcoidosis." (PMID 27929051, 2016). "The differential presence of pro-inflammatory markers such as TNF-α, IL-8, and FLCs may point to a different pathology in the two sarcoidosis subgroups." (PMID 25866481, 2015). "Similar conclusions were also drawn by other authors, who found that peripheral blood mononuclear cells (PBMNC) isolated from sarcoidosis patients released higher amounts of various cytokines involved in the pathogenesis of sarcoidosis (such as IL-1β, TNF-α, IL-6, and GM-CSF), compared to controls." (PMID 26445225, 2015). "Furthermore, BAL cells of sarcoid patients produced inflammatory cytokines (TNF-α and GM-CSF) upon stimulation with P. acnes indicating potential involvement of this pathogen in the pathogenesis of sarcoidosis in some patients." (PMID 26204953, 2015). "Furthermore, BAL cells of sarcoid patients produce inflammatory cytokines (TNF-α and GM-CSF) upon stimulation with heat-killed P. acnes suggesting involvement of this pathogen in the pathogenesis of sarcoidosis." (PMID 26204953, 2015). "A recent study on skin and lung sarcoidosis patients suggests that blockage of TNF may result in more favorable therapeutic effects for the skin than that of p40 blockade for the time period observed." (PMID 27747495, 2015). "This case report will support further studies to clarify TNF inhibitor induced sarcoidosis." (PMID 25097790, 2014). "However in the past few years, there are small number of literatures possible that involve TNF therapy, mainly etanercept, in the development of pulmonary aseptic granulomatosis such as sarcoidosis." (PMID 25097790, 2014). "In the present case, anti-TNFα was started after the diagnosis of sarcoidosis." (PMID 24653848, 2014). "It seems reasonable that TNF inhibitor would be useful for granulomatous disease, like sarcoidosis." (PMID 25097790, 2014). "Similarly, after administration of anti-TNF-alpha in patients with AS, emergence of sarcoidosis was reported." (PMID 24741443, 2014). "This article presents the first report of sarcoidosis treated with etanercept, adding this drug as an option for refractory patients who failed other TNF-α inhibitors, having the advantage of not being associated with development of neutralizing antibodies." (PMID 25494723, 2014). "Epidemiological data supported that the increased production of tumor necrosis factor (TNF) family members may have physiological implications on the development of sarcoidosis." (PMID 24244632, 2013). "TNF production is a fundamental part of the immunologic process of sarcoidosis." (PMID 23533794, 2013). "This meta-analysis extended previous findings on the association between the TNF-α and TNF-β genetic polymorphisms and sarcoidosis, by showing that the TNF-β gene A252G polymorphism might be a potential risk factor for the development of sarcoidosis." (PMID 24244632, 2013). "As the role of TNF-α in the pathogenesis of SFN in sarcoidosis appears interesting to explore, anti-TNF therapy might be beneficial in the treatment of SFN in sarcoidosis." (PMID 23304492, 2012). "In addition, TNFα is also expressed by Th1 and Th17 cells and both T helper cell subsets are likely involved in sarcoidosis pathogenesis." (PMID 22513006, 2012). "The role of TNF-α in the pathogenesis of SFN in sarcoidosis appears interesting to explore." (PMID 23304492, 2012).
sarcoidosis (continued). "Finally, mo-DCs from sarcoidosis patients induce more TNFα in co-cultures with allogeneic CD4+ T cells, compared to mo-DCs from healthy controls." (PMID 22513006, 2012). "Taken together, these data show that DCs from sarcoidosis patients examined outside of the disease microenvironment were not intrinsically more mature, but do show an increased propensity to induce the production of TNFα, a cytokine pivotal in sarcoidosis pathogenesis." (PMID 22513006, 2012). "Uncomplicated sarcoidosis cases trended toward higher corticosteroid usage whereas complicated sarcoidosis cases trended toward higher methotrexate usage and were more likely to be receiving anti-TNFα therapy." (PMID 22984568, 2012). "This case supports the idea that TNF-α may be a crucial cytokine in the pathogenesis of SFN related to sarcoidosis and presumably in SFN related to other immune-mediated inflammatory diseases as well." (PMID 23304492, 2012). "Tumor necrosis factor (TNF)-α and type I interferon (IFN) are cytokines with important roles in coordinating immune reactions, and potentially contribute to the local and systemic inflammatory processes underlying sarcoidosis pathogenesis." (PMID 22195005, 2011). "Based upon the literature, we developed a computational model of known interactions between essential immune cells (antigen-presenting macrophages, effector and regulatory T cells) and cytokine mediators (IL-2, TNFα, IFNγ) of granulomatous inflammation during sarcoidosis." (PMID 21637752, 2011). "Similar to TNF-α, type I IFN has also been implicated in sarcoidosis pathogenesis." (PMID 22195005, 2011). "In this regard, it is interesting that the current model assumptions predict that monotherapy with anti-TNFα would either be ineffective or could paradoxically promote the sarcoidosis state." (PMID 21637752, 2011). "TNF-α inhibitors are currently used off-label in sarcoidosis." (PMID 22195005, 2011). "Whereas there are studies which report the minor TNFA-308A allele (allele 2) to be associated with higher inducible levels of gene transcription and TNF-α production, our earlier study in sarcoidosis patients found the G allele for this polymorphism to be associated with high sTNF-α levels." (PMID 20537163, 2010). "Additionally, alveolar macrophages release a variety of cytokines, including TNF-alpha, IL-1, IL-6, IL-12, IL-15, and growth factors in patients with sarcoidosis and pulmonary disease." (PMID 18811966, 2008). "Therefore, inhibition of TNFα can be an effective strategy for the treatment of sarcoidosis." (PMID 38592130, 2024). "Since our study focused on TNF‐alpha antagonists, comparing the efficacy of this treatment modality alone versus combination therapies may help elucidate the mechanisms of action of multiple immunosuppressive drugs in sarcoidosis." (PMID 38087813, 2024). "Thus, the development of sarcoidosis-like reactions is mediated by a dysregulated activation of T lymphocytes, which triggers the release of IL-2 and the activation of macrophages, which in turn produce large amounts of TNF-α." (PMID 39590170, 2024). "However, there have been isolated cases of sarcoidosis occurrence during anti-TNF therapy." (PMID 37175894, 2023). "Drug-induced sarcoidosis (antiretroviral therapy, TNF-α antagonists, interferon therapy, and immune checkpoint inhibitors) can only be speculated because of the surprising clinical and histological similarity between the two entities in terms of immunopathogenesis." (PMID 37108489, 2023). "However, it is important to note that anti-TNF therapies can paradoxically lead to sarcoidosis-like reactions, which may require discontinuation of the treatment." (PMID 37483590, 2023). "For example, anti-TNF in sarcoidosis may induce psoriasis skin lesions." (PMID 33324666, 2020).